INS (insulin)
Diseases named in the same sentence as INS in open-access papers (continued):
Sharing a sentence is not in itself a finding about the gene and the disease.
Insulin resistance (continued). "Obesity is associated with insulin resistance and consequently higher rates of circulating insulin leading to a higher bioactivity of Insulin-like-growth factor 1 (IGF-1)." (PMID 31052303, 2019). "T2D is characterized by insulin resistance (IR) through which insulin target tissue is unable to respond normally to insulin reflecting insulin deficiency." (PMID 31214116, 2019). "Both types are characterized by hyperglycemia due to either insufficient insulin production (T1D) or loss of cellular sensitivity to insulin, known as insulin resistance (T2D)." (PMID 31683538, 2019). "PTP1B-deficient animal model also possesses a lower risk of insulin resistance and obesity and exhibits improved insulin sensitivity in peripheral tissues." (PMID 31035653, 2019). "T2D, characterized by insulin resistance and defective insulin signaling, is a common co-morbidity and a risk factor for AD, increasing the risk approximately two to fourfold." (PMID 31275108, 2019). "Mice lacking PRDX6 but fed with SCD develop a mild form of DM, mainly linked to higher levels of insulin resistance associated with a defect of glucose-stimulated insulin secretion (GSIS)." (PMID 31949886, 2019). "Because of this rapid and substantial increase in circulating insulin, we studied the expression of a number of well-characterized genes recognized to correlate with insulin resistance." (PMID 30794724, 2019). "A strong association between levels of leptin, insulin and homeostatic model assessment of insulin resistance index (HOMA-IR) was also found in GD1 subjects." (PMID 31791361, 2019). "The vast majority of loci related to T2DM is primarily associated with insulin secretion and β‐cell function with far fewer variants apparently influencing insulin resistance." (PMID 31250990, 2019). "Before the onset of type 2 diabetes, insulin resistance causes hyperproduction of insulin to overcome the insulin resistance of muscle, adipose tissue, and the liver." (PMID 31075957, 2019). "Chronic low-grade inflammation in insulin-sensitive tissues, such as the liver and visceral adipose tissue, is central to obesity-associated insulin resistance, glucose intolerance, and NAFLD progression." (PMID 30818779, 2019). "Hypothalamic insulin resistance caused by excessive nutrition occurs more rapidly than that in other insulin-sensitive tissues." (PMID 30875909, 2019). "Obesity is a major risk factor for developing systemic insulin resistance, and skeletal muscle is the first tissue in susceptible individuals to lose its insulin responsiveness." (PMID 31195596, 2019). "CH and SCH are associated with some metabolic disorders including insulin resistance or high insulin levels, dyslipidemia, obesity, and endothelial dysfunction, which are closely associated with atherosclerosis and cardiovascular risk." (PMID 31380419, 2019). "Insulin has been proven essential to optimal hippocampal memory processes, and insulin resistance in the telencephalon can result in cognitive deficiencies, which usually accompany type-II diabetes." (PMID 31311133, 2019). "Elements that reduce IRS-1 phosphorylation or activate serine IRS-1 phosphorylation at the 307 site cause defects in insulin signal transduction, ultimately resulting in insulin resistance." (PMID 31035653, 2019). "Reduced sensitivity to insulin in skeletal muscle is also a pathophysiological hallmark of type 2 diabetes, and insulin resistance is an early predictor of this disease (Warram, Martin, Krolewski, Soeldner, & Kahn, 1990)." (PMID 31724339, 2019). "Protein tyrosine phosphatase 1B (PTP1B) regulates insulin signaling negatively, and its increased activity and expression are implicated in the pathogenesis of insulin resistance." (PMID 30680174, 2019). "The deregulation of insulin signaling pathways is the main factor causing reduced insulin sensitivity and then insulin resistance, and insulin resistance is the most frequent cause for T2DM." (PMID 31266190, 2019).
Insulin resistance (continued). "The accumulation of fat in insulin sensitive tissues such as skeletal muscle and liver has been related to the development of insulin resistance and, consequently, increases the risk for developing Type 2 Diabetes and cardiovascular disease." (PMID 31581241, 2019). "Insulin resistance is an additional risk factor for AD whereby decreased insulin signaling increases synaptic sensitivity to amyloid beta (Aβ) and tau." (PMID 31160730, 2019). "Obesity is associated with insulin resistance both in in vivo models and in humans, and the adipogenic stimuli, insulin, activates the MAPK/ERK pathway." (PMID 30621146, 2019). "CEACAM1 is involved in promoting insulin clearance and its loss in hepatic expression has been shown to link insulin resistance to obesity and NAFLD." (PMID 31805072, 2019). "Even if an HFD caused functional damage to glucose and insulin handling, lipotoxicity alone was insufficient to provoke β-cell insulin resistance within 8 wk of diet treatment." (PMID 29957055, 2019). "Dysregulation of critical components of the insulin signalling pathway is associated with the pathogenesis of insulin resistance and hyperglycaemia." (PMID 31300679, 2019). "Decreased skeletal muscle Rac1 signaling has been associated with insulin resistance in insulin resistant obese and type 2 diabetic human subjects, as well as in diabetic ob/ob mice and diet-induced obese insulin resistant rodents." (PMID 31075957, 2019). "Caused by chronic hyperglycemic stress, insulin resistance (IR) impairs insulin signal transduction and leads to the development of NAFLD." (PMID 30881473, 2019). "Resistin has previously been shown to inhibit insulin-stimulated glucose uptake in skeletal muscle of rats, and elevated levels have been proposed as a cause of obesity-related insulin resistance in rodents and humans." (PMID 31533709, 2019). "DD can be a major event during the young onset (11–19 years old) of diabetic patient, as a result of weight gain and insulin resistance caused as side effects of insulin treatment." (PMID 31685799, 2019). "Obesity is a pivotal cause of insulin resistance, and the changes in insulin sensitivity through pregnancy are partly related to maternal fat mass." (PMID 31828161, 2019). "It is well known that the hexosamine pathway can induce insulin resistance through direct post-translational modification of key insulin signaling proteins, via O-linked glycosylation on serine and threonine residues with the GlcNAc moiety." (PMID 30832230, 2019). "We have presented in this study that C/EBP-α, FOXO1, PPAR-γ2 and IGFBP-2 have an interesting association in insulin resistance associated with obesity: their expression profile was found altered in adipose tissue in an insulin-dependent manner." (PMID 31547433, 2019). "Current research has shown that hepatic fatty acid accumulation can cause hepatic insulin resistance through increased gluconeogenesis, lipogenesis, chronic inflammation, oxidative stress and endoplasmic reticulum stress, and impaired insulin signal pathway." (PMID 31649547, 2019). "Ectopic fat in skeletal muscle and the liver has been shown to cause insulin resistance associated with NAFLD via impaired insulin signaling by diacylglycerol activation of protein kinase C50." (PMID 31087530, 2019). "The degree of adipose infiltration into skeletal muscle, the liver, and other organs is associated with increased triglyceride content and reduced insulin-stimulated glucose uptake, which interferes with insulin signalling and leads to insulin resistance." (PMID 31888500, 2019). "The immune activation associated with HIV infection is also associated with a state of peripheral insulin resistance and reduced insulin secretion, hence increasing the risk of DM and metabolic syndrome at an early age." (PMID 30783538, 2019).
Insulin resistance (continued). "In the same line, Blautia increased in UM-A mothers, which was described to be inversely associated with insulin and homeostatic model assessment of insulin resistance (HOMA-IR) values in gestational diabetes mellitus mothers." (PMID 31484413, 2019). "The present study confirms findings from previous studies regarding a positive association between depression and insulin resistance indices (i.e., insulin, QUICKI." (PMID 31260504, 2019). "Insulin resistance is a hallmark of metabolic diseases, resulting in the impaired ability of insulin to suppress liver gluconeogenesis, while maintaining its ability to stimulate lipogenesis." (PMID 30987128, 2019). "Devevre and coworkers previously demonstrated that serum insulin is significantly associated with classical, intermediate, and nonclassical monocyte subpopulations of morbidly obese patients with insulin resistance." (PMID 31183389, 2019). "Obesity is associated with low grade inflammation which occurs in peripheral metabolic tissues, resulting in whole body insulin resistance, but also in the hypothalamus causing local impairment of insulin signaling and sensitivity." (PMID 30906281, 2019). "A major metabolic defect associated with insulin resistance is the failure of peripheral insulin sensitive tissues, such as, adipose, muscle, and liver to properly utilize glucose." (PMID 31443389, 2019). "The different mechanisms explain the causes of insulin resistance in diabetic patients are: abnormal insulin production; impaired post-receptor signaling (major cause); insulin receptor mutation; and the presence of an insulin antagonist in the body." (PMID 31480505, 2019). "By contrast, T2DM is caused by insulin resistance that often presents with deficient β-cell insulin secretion due to an inability to overcome persistently elevated blood glucose levels." (PMID 31614631, 2019). "Since impaired insulin secretion and insulin resistance are two leading pathological causes of T2DM, identification of effective molecular mechanisms in these events is necessary for the prevention and treatment of T2DM." (PMID 32133058, 2019). "DM is caused by autoimmune insulin depletion or acquired insulin resistance which give rise to chronic elevated blood glucose levels." (PMID 31614631, 2019). "Intravenous (IV) delivery of an adeno-associated virus vector serotype 8 encoding Ucn2 (AAV8.Ucn2) increases insulin sensitivity and glucose disposal in mice with insulin resistance." (PMID 31790421, 2019). "Insulin resistance or deficiency of insulin secretion in diabetic patients type 2 cause chronic hyperglycemia and impaired carbohydrates, lipids, and protein metabolism and ultimately promote the generation of reactive oxygen species and oxidative stress." (PMID 30858941, 2019). "For smoking, the nicotine in tobacco can raise blood sugar levels by increasing the levels of norepinephrine, epinephrine, glucocorticoid, and growth hormone glucagon levels in the body and can also reduce insulin secretion, thus causing insulin resistance." (PMID 30911549, 2019). "The vitamin D levels were significantly associated with the glycemic markers of insulin resistance, such as fasting glucose, fasting insulin, and HOMA-IR." (PMID 31151163, 2019). "Changes in fatty acid composition of the diet were associated with changes in insulin resistance and insulin secretion." (PMID 30871233, 2019). "Previously, the hyperinsulin-induced decrease in cellular insulin activity has been reported in myocytes and adipocytes as well as in the nervous system, which in turn causes insulin resistance." (PMID 31635074, 2019). "Obesity is associated with insulin resistance both in in vivo models and human models, and adipogenic stimuli like insulin activates the MAPK/ERK pathway." (PMID 30621146, 2019).
Insulin resistance (continued). "In humans, lipoatrophy was shown to drive systemic insulin resistance, while disruption of the insulin signalling cascade in adipocytes in mice causes lipoatrophy and promotes the development of type 2 diabetes." (PMID 31309261, 2019). "Insulin resistance, a hallmark of T2D, is characterized by compromised insulin-mediated activation of the PI3K/Akt pathway regulating glucose uptake via Glut4 transporters." (PMID 31266232, 2019). "Increasing studies have unveiled that exosomes derived from the insulin-resistant adipocyte were implicated in the skeletal muscle insulin resistance, obesity-related liver disease, atherosclerosis, and lung cancer." (PMID 31407623, 2019). "It has been believed that hypertension can cause insulin resistance by altering the delivery of insulin and glucose." (PMID 30934575, 2019). "It is well established that PCOS is associated with defects in insulin secretion and profound insulin resistance." (PMID 31737638, 2019). "Diabetes mellitus is a chronic endocrine disorder caused by lifestyle changes or inadequate insulin secretion due to hereditary factors, islet dysfunction, or development of insulin resistance." (PMID 31662781, 2019). "As for acne vulgaris and hidradenitis suppurativa, mechanistic target of rapamycin complex 1 (mTORC1) is the key element that associates with insulin signaling and insulin resistance." (PMID 31824416, 2019). "In patients with early stages of T2D, β-cells secrete excessive insulin and expand their mass to compensate for the increased metabolic load and obesity-associated insulin resistance." (PMID 30953560, 2019). "The uneven distribution of fat in insulin sensitive organs like the liver or pancreas increases the risk for development of insulin resistance, T2D, and non-alcoholic fatty liver disease (NAFLD), which are common in Indians." (PMID 31369557, 2019). "Type II diabetes mellitus (T2DM) is typically caused by nutritional, lifestyle, and genetic factors causing obesity-induced insulin resistance and eventual depletion of insulin-secreting cells altogether." (PMID 31921122, 2019). "Failure of INSR internalization leads to prolonged insulin existence in circulation causing hyperinsulinemia and further aggregates insulin resistance as shown in patients with an arginine to cysteine 252 mutation in INSR." (PMID 31658625, 2019). "AKT inhibition is a hallmark of insulin resistance, characterized by the failure of insulin to promote glucose uptake by the muscle and to inhibit gluconeogenesis in the liver." (PMID 30987128, 2019). "We performed histological and molecular studies for patients referred to our French National Reference Center for Rare Diseases of Insulin Secretion and Insulin Sensitivity for lipodystrophy and/or insulin resistance and carrying PLIN1 frameshift variants." (PMID 31504636, 2019). "In a series of chronic malignant cycles, patients can develop type 1 diabetes caused by insufficient insulin secretion or type 2 diabetes caused by insulin resistance." (PMID 31119181, 2019). "In the insulin resistance background, a major feature is abnormal glucose and lipid metabolism caused by an abnormal response to insulin, impaired muscle glucose uptake, muscle and liver glycogen synthesis, and overt hyperglycemia." (PMID 31212747, 2019). "The changes in serum glucose concentrations during OGTT were associated with insulin secretion and insulin resistance." (PMID 31777424, 2019). "Insulin resistance in effect equates with a cluster of risk factors, namely, resistance to insulin-stimulated glucose uptake, glucose intolerance, and hyperinsulinemia." (PMID 31396410, 2019). "Not only insulin resistance and inflammation participate in appetite regulation, but the expression of genes in abdominal fat associated with insulin metabolism can also regulate appetite." (PMID 31191339, 2019).
Insulin resistance (continued). "Genetically predicted insulin, BMI-adjusted insulin and insulin resistance score were all positively associated with MI overall and also in men, but not in women (p values for sex differences were 0.02, 0.04 and 0.04 respectively)." (PMID 31508506, 2019). "Elevated fasting circulating insulin concentrations (or insulin resistance) are independently associated with an exacerbated risk of hypertension in the general population." (PMID 31121885, 2019). "Insulin resistance causes a reduction in antilipolytic activity of insulin, which subsequently increases hepatic triglyceride synthesis." (PMID 31597283, 2019). "Insulin resistance is strongly associated with the ectopic lipid accumulation in insulin-target tissues." (PMID 31680948, 2019). "Skeletal muscle is a crucial metabolic organ for insulin-stimulated glucose disposal, and has been implicated in insulin resistance and obesity." (PMID 31545909, 2019). "In high-fat-diet (HFD)-induced obesity, G6PD-deficient mice have decreased insulin and Homeostatic Model Assessment for Insulin Resistance (HOMA-IR) index." (PMID 31500396, 2019). "Xanthurenic acid forms a complex with insulin, which causes a decline in sensitivity to insulin and decreases its activity, thus, leading to insulin resistance typical of MetS." (PMID 30862026, 2019). "Although a delayed peak of insulin is generally associated with insulin resistance, it is often related to an increased glucose concentration and area-under-curve, which is not the case in our study." (PMID 31653107, 2019). "The results obtained identified an methylome specific of insulin resistance in visceral adipose tissue, in which potential epigenetic biomarkers and new therapeutic targets for the alterations in insulin sensitivity associated with obesity were identified." (PMID 31040824, 2019). "Greater PDH activity caused by global PDK 2/4 deficiency improves insulin sensitivity, suggesting PDKs are involved in the development of whole-body insulin resistance." (PMID 31134063, 2019). "Their study also revealed that, in humans, plasma BAIBA levels were increased with exercise and inversely associated with metabolic risk factors, such as fasting glucose, insulin, homeostasis model assessment of insulin resistance (HOMA-IR), TG, and TC levels." (PMID 30858489, 2019). "To satisfy the first assumption, we used genetic variants strongly associated with insulin and insulin resistance from a large GWAS27,29, as previously." (PMID 31508506, 2019). "Impaired insulin secretion by β-cells is a causal factor in the development of T2DM concomitant with insulin resistance." (PMID 31035653, 2019). "The resulting decrease in insulin secretion along with increasing insulin resistance leads to a loss in glycemic control and dangerous elevations in blood glucose levels." (PMID 30875966, 2019). "Less clear is how these insulin actions are mediated, and why they are inextricably linked to the pathogenesis of insulin resistance that is the forerunner of aging-related type-2 diabetes." (PMID 31246177, 2019). "Vitamin D levels were inversely associated with BMI, WC, fasting glucose, fasting insulin, total cholesterol, TG levels, and the homeostatic model assessment for insulin resistance (HOMA-IR) (p < 0.05)." (PMID 31151163, 2019). "A minor part of these loci is associated with a higher susceptibility for increased insulin resistance; however, most loci are associated with altered insulin secretion and beta-cell function." (PMID 31828161, 2019). "Chi-square tests, logistic regression, and linear regression were used to estimate the relationships of SNPs with GDM risk and oral glucose tolerance test (OGTT), fasting insulin, and homeostasis model assessment of insulin resistance (HOMA-IR) levels." (PMID 30805369, 2019). "This has also been proposed by in vitro studies of muscle showing that ceramide-induced insulin resistance was associated with marked impairments in insulin-induced Rac1 activation." (PMID 31075957, 2019).